TRPM8 (transient receptor potential cation channel subfamily M member 8)
Diseases named in the same sentence as TRPM8 in open-access papers (continued):
Sharing a sentence is not in itself a finding about the gene and the disease.
osteosarcoma (15 papers, 2015 to 2025). A usually aggressive malignant bone-forming mesenchymal neoplasm, predominantly affecting adolescents and young adults. "For example, the regulation of proliferation in cancer cell lines has been proven by siRNA experiments, in which downregulation of TRPM8 caused the reduction of prostatic and osteosarcoma cancer cell proliferation and cell cycle progression." (PMID 27289382, 2016). "For instance, TRPM8-mediated proliferation, migration, and invasion in osteosarcoma cells are associated with activation of AKT-GSK-3β and phosphorylation of extracellular growth factor-regulated kinase (ERK) and focal adhesion kinase (FAK)." (PMID 26512697, 2015). "Taken together, TRPM8 is upregulated in both osteosarcoma cell lines and osteosarcoma samples, and such upregulation has an indicative role in predicting patients’ prognosis." (PMID 35361751, 2022). "Molecularly, AMTB specifically antagonizes TRPM8 which is upregulated in osteosarcoma and its expression level in osteosarcoma tissues is negatively related to patients’ prognosis." (PMID 35361751, 2022). "In summary, our study revealed an upregulation of TRPM8 in osteosarcoma, and the expression level of TRPM8 is negatively related to patients’ prognosis." (PMID 35361751, 2022). "Conclusively, the function of TRPM8 is necessary to sustain proliferation and migration for osteosarcoma cells." (PMID 35361751, 2022). "Results indicate that TRPM8 is overexpressed in all four osteosarcoma cell lines, with at least two-fold increase as compared to that in MSC." (PMID 35361751, 2022). "This androgen receptor (AR)–dependency of TRPM8′s role in proliferation has also been observed in cells from other cancers, such as colon, osteosarcoma, and lung cancer." (PMID 35743115, 2022). "Here, we used N-(3-aminopropyl)-2-[(3-methylphenyl) methoxy] -N-(2-thienylmethyl) benzamide hydrochloride (AMTB), a specific TRPM8 antagonist, to explore its antitumoral effect on osteosarcoma." (PMID 35361751, 2022). "The proliferative role of TRPM8 in osteosarcoma (OSS) is demonstrated in osteosarcoma cancer cells lines, MG-63 and U2OS, where TRPM8 is aberrantly over-expressed." (PMID 36844925, 2022). "Expression level of TRPM8 was examined in 4 osteosarcoma cell lines (143B, U2OS, MG63, and HOS) and human mesenchymal stem cells (hMSC) using Western blot assay." (PMID 35361751, 2022). "In the present study, we demonstrated an upregulation of TRPM8 in osteosarcoma cell lines compared to MSC." (PMID 35361751, 2022). "In order to probe for the functionality of TRPM8 in bone cells, Ca2+-imaging was performed using Fluo4-AM loaded into Saos2 cells (Human osteosarcoma cell line)." (PMID 33580126, 2021). "Increasing evidence indicates that the abnormal expression of TRPM8 is associated with various types of cancer, including pancreatic, prostate, breast, lung, and colon cancer and osteosarcoma; TRPM8 channels contribute to tumor growth and metastasis." (PMID 33344232, 2020). "Just like in osteosarcoma, the TRPM8 channel is expressed at high levels, and acts as modulator of the invasion potential in Squamous Cell Cancer (SCC)." (PMID 29875336, 2018). "High-level TRPM8 expression was also detected in human osteosarcoma cell line Saos2." (PMID 33580126, 2021). "The first study analyzing TRP channels in sarcomas reported a marked increase of the expression of the TRP melastatin (TRPM8) subfamily in patients with osteosarcoma at a higher clinical stage compared to those with a lower clinical stage and the absence of metastasis." (PMID 33076385, 2020). "On the other hand, an inhibition of TRPV1-induced Ca2+ influxes by 3-T1AM-based TRPM8 activation through a negative feedback was observed in human corneal epithelial cells, and cancer cells, such as TRPM8 transfected U2osB2 osteosarcoma, WERI-Rb1 retinoblastoma, and human uveal melanoma (UM 92-1)." (PMID 31141957, 2019). "TRPM8 is also involved in osteosarcoma, by mediating proliferation and metastasis." (PMID 29875336, 2018).
osteosarcoma (continued). "Similarly, anti-TRPM8 siRNA decreased the ability of cell adhesion and invasion in lung cancer and osteosarcoma cells." (PMID 26512697, 2015). "Notably, strong staining for TRPM8 in clinical samples is found relevant with patients’ overall survival, verifying its potential role as a molecular marker and prognostic indicator in osteosarcoma (OS: 40.0 ± 5.8 months vs 21.6 ± 2.6 months, p = 0.008)." (PMID 35361751, 2022). "Moreover, TRPM8 knockdown in osteosarcoma cells enhances the cytotoxic effect of epirubicin." (PMID 32575381, 2020). "TRPM8 seems to have a role in cancer cell proliferation and metastasization, since the incubation of osteosarcoma cell lines with AMTB, a TRPM8 antagonist, suppressed such processes and induced apoptosis through the regulation of TGF-β pathways." (PMID 39940997, 2025). "By disturbing the function of TRPM8, AMTB can suppress the development and the progression of osteosarcoma." (PMID 35361751, 2022). "Treatment of several osteosarcoma cell lines (143B, U2OS, HOS, and MG-63), with AMTB, a TRPM8 antagonist, results in suppressed proliferation and metastasis, and induces cellular apoptosis." (PMID 36844925, 2022). "Next, we detected the expression of TRPM8 in 57 human osteosarcoma samples and paired adjacent non-tumoral samples." (PMID 35361751, 2022). "After knockdown of TRPM8, the IC50 value for the osteosarcoma cells was markedly increased." (PMID 35361751, 2022). "Our study provides evidence that TRPM8 could be a potential therapeutic target and AMTB can suppress growth and metastasis of osteosarcoma cells through repressing the TGFβ signaling pathway and increase the sensitivity of tumor cells to cisplatin." (PMID 35361751, 2022). "In compliance with previous observations, 47/57 (82.5%) osteosarcoma samples and only 8/57 (14%) adjacent non-tumoral samples were tested positive for TRPM8, verifying a differential expression of TRPM8 between osteosarcoma and adjacent non-tumoral tissues (p = 0.001)." (PMID 35361751, 2022). "In addition, through analyzation of clinical samples, we also observed a differential expression of TRPM8 between osteosarcoma and adjacent non-tumoral tissues." (PMID 35361751, 2022).
colon cancer (14 papers, 2010 to 2025). "In addition to its association with colon cancer, TRPM8 also plays a role in the prevalent liver metastasis of colon cancer." (PMID 39062591, 2024). "Furthermore, TRPM8 is implicated in colon cancer, playing a pivotal role in the initiation, progression, and metastasis of the disease." (PMID 39062591, 2024). "Overexpression of the Wnt/β-catenin pathway contributed to colorectal cancer development, with a positive correlation with the level of the transient receptor potential (TRP) cation channel, subfamily melastatin (M), member 8 (TRPM8) in primary colon tumours." (PMID 40183090, 2025). "The expression of TRPM8 in colon cancer has been elucidated, showcasing the potential inhibition of colon cancer onset by the TRPM8 antagonist cannabinol." (PMID 39062591, 2024). "The antagonist cannabinol and the agonist WS12 for TRPM8 can rapidly desensitize and inhibit the growth of colorectal cancer xenografts and the occurrence of chemically induced colon cancer, highlighting the potential of TRPM8 as a CRC drug target." (PMID 39633507, 2024). "Gene enrichment analysis demonstrated that the high expression of TRPM8 is associated with the excessive activation of the Wnt-Frizzled signal and the downregulation of Adenomatous polyposis coli (APC) in colon cancer patients." (PMID 39633507, 2024). "This inhibition can impede the advancement of colon cancer, selectively restraining the proliferation of colorectal cancer cells, an effect shared by other TRPM8 antagonists." (PMID 39062591, 2024). "A heightened expression of TRPM8 in human colon cancer has been shown, particularly in cases with liver metastasis." (PMID 39062591, 2024). "The in vitro investigations of one study validated the increased TRPM8 expression in colon cancer cells and further explored a model for colon cancer liver metastasis." (PMID 39062591, 2024). "For instance, the upregulation of TRPM8 in colon cancer cells has been related to higher proliferation, migration, invasion, and metastasis of tumor cells." (PMID 37033630, 2023). "Colon cancer liver metastasis has been connected with TRPM8 over-expression, and TRPM8 silencing decreased cell invasion and migration, possibly through the downregulation of p-AKT/AKT, p-GSK3β/GSK3β expression." (PMID 34445208, 2021). "Increasing number of studies demonstrated that TRPM8 channel is upregulated in various types of cancer, including prostate, pancreatic, breast, lung, and colon cancer and is considered a valuable prognostic marker and putative therapeutic target." (PMID 33344232, 2020). "TRPM8 proteins were also observed in human colon cancer tissue and in a lesser extent in MCF-7 cells (lanes 1-2)." (PMID 20482834, 2010). "This phenomenon might be linked to TRPM8 gene silencing, inhibiting the protein kinase B (Akt)/GSK-3β pathway, thereby impeding colon cancer cell progression, EMT, and subsequent liver metastasis." (PMID 39062591, 2024). "Consequently, TRPM8 emerges as a prospective prognostic, tumor, and therapeutic marker for both colon cancer and liver metastasis in colon cancer." (PMID 39062591, 2024). "The authors recorded a significant decrease in clone number, cell invasion, migration capabilities, and liver metastasis proportion following TRPM8 gene silencing, indicating that TRPM8 upregulation may foster colon cancer liver metastasis." (PMID 39062591, 2024). "TRPM8 may also promote the progress of EMT in colon cancer cells through the AKT/GSK3β signaling pathway, facilitating liver metastasis." (PMID 39633507, 2024). "By contrast, the ethyl acetate was more effective as cytotoxic agent against colon cancer cells, and this could be related, albeit partially, to the content of thymol and to its putative ability to downregulate TRPM8 gene expression." (PMID 36903991, 2023). "Indeed, in human intestine, TRPM8 expression has been associated with pathological conditions such as IBD and colon cancer." (PMID 32751347, 2020).
colon cancer (continued). "Similarly, the Cannabis derivative cannabigerol with blocking activity of the TRPM8 channel induced apoptosis in colon cancer cells." (PMID 26512697, 2015). "By contrast, the ethyl acetate was more effective as cytotoxic agent against colon cancer cells, and this could be related, albeit partially, to the content of thymol and to its ability to downregulate the gene expression of TRPM8, an endovanilloid receptor possibly involved in colon carcinogenesis." (PMID 36903991, 2023). "Transcripts encoding TRPM8 were detected in colon cancer but not in the corresponding normal human tissues and increased TRPM8 expression has been revealed in colonic biopsy material from inflammatory bowel disease (IBD) patients as compared to healthy controls." (PMID 32751347, 2020). "We detected TRPM8 mRNA in MCF-7 cells, and in human colon cancer tissue which was used as a positive control." (PMID 20482834, 2010). "Moreover, silencing of TRPM8 leads to the inhibition of EMT and decreases the proliferation, migration, invasion, and metastasis of colon cancer cells, proving the importance of the channel in these processes." (PMID 37033630, 2023). "Additionally, in colon cancer HCT116 cells, the gene expression of transient receptor potential cation channel subfamily M (melastatin) member 8 (TRPM8), possibly involved in colon carcinogenesis, was conducted as well." (PMID 36903991, 2023). "The calcium-permeable cation channel TRPM8 (transient receptor potential melastatin 8) is a member of the TRP superfamily of cation channels that is upregulated in various types of cancer with high levels of autophagy, including prostate, pancreatic, breast, lung, and colon cancers." (PMID 33344232, 2020).
colorectal cancer (14 papers, 2012 to 2025). A primary or metastatic malignant neoplasm that affects the colon or rectum. "According to previous studies, colorectal cancer is linked to a transient receptor potential channel in the calcium signaling pathway called TRPM8, and ingredients of the calcium signaling system are rearranged, altered, or deregulated in cancer." (PMID 40559953, 2025). "TRPM8 not only impacts the liver metastasis of colorectal cancer but also fosters the onset and progression of hepatocellular carcinoma itself." (PMID 39062591, 2024). "Another study showed that TRPM8 activation can inhibit the development of colorectal cancer by suppressing the Wnt/β-catenin signaling pathway." (PMID 38280896, 2024). "The overexpression of some TRP channels in colorectal cancer is related to increased activity of JNK and p38 signaling pathways through TRPM8 or TRPV4 type channels, both associated with calcium entry into the cytoplasm." (PMID 39272835, 2024). "Recent research reports that TCAF2 in peritumoral stromal cells promotes liver metastasis in colorectal cancer by inhibiting the cold-sensing TRPM8 channel." (PMID 38019450, 2024). "In addition, administration of D-3263 increases the cytotoxicity of 5-FU/Oxaliplatin in patient-derived colorectal cancer organoids, depending on the levels of TRPM8." (PMID 40405392, 2025). "Conversely, certain studies propose that TRPM8 inhibits the liver metastasis of colorectal cancer." (PMID 39062591, 2024). "Additionally, an investigation into the relationship between TRPM8 expression and the survival rates of colorectal cancer patients revealed a lower survival rate among those with elevated TRPM8 expression." (PMID 39062591, 2024). "Recent pharmacological investigations have validated that TRPM8 blockade can diminish tumor growth in colorectal cancer xenograft mice by downregulating the transcription of Wnt signaling regulators and tempering the activation of β-catenin, alongside its target oncogenes like C-Myc and Cyclin D1." (PMID 39062591, 2024). "An increase in the expression of TRPM8 significantly increased the conversion of LC3-I to LC3-II and activated basal level of autophagy in adenocarcinoma MCF7 cells and colorectal carcinoma HCT116 cells." (PMID 33344232, 2020). "Proliferation assays performed on Caco-2 and SW620 with the P2Y1 or RAGE inhibitor demonstrated that iPolyP mainly triggers colorectal cancer cell expansion by binding to TRPM8, as the hindrance of these pathways did not affect the proliferation induced by iPolyP." (PMID 39409946, 2024).
lung carcinoma (13 papers, 2010 to 2023). "In Lewis lung cancer cells, the expression of TRPA1 and TRPM8 is linked with autophagy, tumor cell metastasis, and energy metabolism." (PMID 36090899, 2022). "With the exclusion of the liver where the amount declines upon malignant transformation, TRPM8 mRNA rises in several types of tumors with groups of bladder, breast, kidney and lung cancer samples characterized by particularly high expression of the channel." (PMID 33288740, 2020). "TRPM8 overexpression stimulates the progression of prostate cancer, lung cancer, and osteosarcoma 13-15." (PMID 32929340, 2020). "Consistent with the anti-proliferative role of TRPM8 in PC-3 cells, siRNA-mediated down-regulation of TRPM8 promoted cell proliferation of lung cancer cells LLC-2." (PMID 26512697, 2015). "The previous results suggest that expression levels of TRPM8 are relevant in lung cancer." (PMID 37033630, 2023). "Lung adenocarcinoma overexpresses TRPM8, and this expression is negatively correlated with survival rate in patients according to the TCGA and PROGgene database 47,48, suggesting an important role for TRPM8 in lung cancer intervention." (PMID 32929340, 2020). "On the other hand, in lung carcinoma, the ectopic expression of TRPM8 favors cell propagation." (PMID 27289382, 2016). "Additionally, TRPM8 is considered a cancer marker of lung cancer." (PMID 32929340, 2020). "TRPA1 induced autophagy under adverse conditions, and the combination of TRPM8 and TRPA1 directly contributed to the aggressive phenotype of lung cancer." (PMID 35281822, 2022). "Furthermore, in lung cancer, the enhanced efficiency of the chemotherapeutic doxorubicin (DOX) was reported in A549 cells treated with the TRPM8 agonist borneol." (PMID 37033630, 2023).